ACADM (acyl-CoA dehydrogenase medium chain)
Description:
Medium-chain specific acyl-CoA dehydrogenase is one of the acyl-CoA dehydrogenases that catalyze the first step of mitochondrial fatty acid beta-oxidation (FAO), breaking down fatty acids into acetyl-CoA and allowing the production of energy from fats. The first step of FAO consists in the proR-proR stereospecific alpha, beta-dehydrogenation of fatty acyl-CoA thioesters using the electron transfer flavoprotein (ETF) as their physiologic electron acceptor, resulting in the formation of trans-2-enoyl-CoA ((2E)-enoyl-CoA). ETF is the electron acceptor that transfers electrons to the main mitochondrial respiratory chain via ETF-ubiquinone oxidoreductase (ETF dehydrogenase). Among the different mitochondrial acyl-CoA dehydrogenases, medium-chain specific acyl-CoA dehydrogenase has preference for fatty acyl-CoAs with saturated 6 to 12 carbons long primary chains, making it but can also catalyze longer chains such as C14 and C16.
Synonyms: MCAD; MCADH; ACAD1
Tractability: Small molecule: a structure with a bound ligand is known; it has a high-quality binding pocket. PROTAC: ubiquitination databases record sites on it; its protein half-life has been measured.
Target class: Enzyme; Oxidoreductase
Gene: Protein-coding gene on chromosome 1 (75,724,431 to 75,787,575, forward strand). Ensembl gene ENSG00000117054.
Subcellular location: Mitochondrion matrix
Subcellular location (Human Protein Atlas): Mitochondria; Calyx; Perinuclear theca; Principal piece
Pathways (Reactome):
Metabolism: Beta oxidation of decanoyl-CoA to octanoyl-CoA-CoA; Beta oxidation of octanoyl-CoA to hexanoyl-CoA; PPARA activates gene expression; mitochondrial fatty acid beta-oxidation of unsaturated fatty acids
Gene Ontology:
Molecular function: acyl-CoA dehydrogenase activity; identical protein binding; medium-chain fatty acyl-CoA dehydrogenase activity; flavin adenine dinucleotide binding; long-chain fatty acyl-CoA dehydrogenase activity; oxidoreductase activity, acting on the CH-CH group of donors; short-chain fatty acyl-CoA dehydrogenase activity
Biological process: carnitine biosynthetic process; carnitine metabolic process, CoA-linked; fatty acid beta-oxidation; fatty acid beta-oxidation using acyl-CoA dehydrogenase; medium-chain fatty acid catabolic process; medium-chain fatty acid metabolic process; glycogen biosynthetic process; regulation of gluconeogenesis
Cellular component: axon; mitochondrial matrix; mitochondrial membrane; mitochondrion; nucleus; cytoplasm
Genetic constraint (gnomAD): Loss-of-function variants: 40 observed, 48.56 expected, observed/expected ratio (o/e) 0.82, 90% interval 0.64 to 1.07. The upper end of that interval is the gene's LOEUF score, 1.07, which puts it in group 4 of 6, group 1 being the genes least tolerant of losing a copy. Missense variants: 453 observed, 478.4 expected, observed/expected ratio (o/e) 0.95, 90% interval 0.88 to 1.02. Synonymous variants: 142 observed, 149.8 expected, observed/expected ratio (o/e) 0.95, 90% interval 0.83 to 1.09.
Gene-disease validity (ClinGen):
ClinGen rates the evidence that ACADM causes each of these diseases.
medium chain acyl-CoA dehydrogenase deficiency (autosomal recessive): Definitive.
Homologues: Orthologues: macaque ACADM (97% identical), dog ACADM (90% identical), chimpanzee ACADM (90% identical), mouse Acadm (88% identical), pig ACADM (87% identical), rat Acadm (86% identical), tropical clawed frog acadm (81% identical), rabbit ACADM (80% identical), zebrafish acadm (80% identical), guinea pig ACADM (70% identical), Caenorhabditis elegans acdh-10 (58% identical), Caenorhabditis elegans acdh-8 (57% identical), and 6 more. Paralogues in human: ACADS (34% identical), ACADSB (34% identical), ACAD9 (33% identical), ACADVL (32% identical), IVD (32% identical), ACAD8 (31% identical), ACADL (31% identical), GCDH (26% identical), ACAD10 (25% identical), ACAD11 (24% identical), ACOX3 (21% identical), ACOXL (20% identical), and 2 more.
Diseases named in the same sentence as ACADM in open-access papers:
ACADM is named in the same sentence as 83 diseases in open-access papers, as found by Europe PMC text mining. Sharing a sentence is not in itself a finding about the gene and the disease. The quoted sentences say what the papers report.
MCAD deficiency (33 papers, 2009 to 2026). "MCAD deficiency (MCADD) is an autosomal recessive inherited defect of the medium-chain acyl-CoA dehydrogenase gene (ACADM; 60700) on chromosome one (1p31)." (PMID 41239521, 2025). "A similar case was also reported regarding medium-chain acyl-CoA dehydrogenase deficiency (MCADD) caused by mutations in the ACADM gene." (PMID 39606474, 2024). "Especially, ACADM defect causes medium-chain acyl-CoA dehydrogenase deficiency, which can result in infantile death." (PMID 35761325, 2022). "Biochemical index after treatment and the mutations in the ACADM gene of the medium-chain acyl-CoA dehydrogenase deficiency patients." (PMID 33841490, 2021). "Clinical characteristics and the mutations in the ACADM gene of the medium-chain acyl-CoA dehydrogenase deficiency (MCADD) patients." (PMID 33841490, 2021). "We investigated the frequency of the most common ACADM variant; 985A>G, at that time representing over 90% of the variants identified in clinically diagnosed patients with MCAD deficiency." (PMID 33073033, 2020). "Patients with MCAD deficiency can be identified based on high blood C8 levels, which is due to mutation of the ACADM gene." (PMID 29534692, 2018). "MCAD deficiency is inherited as an autosomal recessive trait and is caused by mutations in the medium-chain acyl-CoA dehydrogenase (ACADM) gene, which is located on chromosome 1p31 and consists of 12 exons spanning 44 Kb." (PMID 24294134, 2013). "In most cases, however, the effect of one single ACADM mutation was studied, although MCAD deficiency is an enzyme deficiency caused by genetic alterations on both ACADM alleles." (PMID 22630369, 2012). "Octanoyl-CoA oxidation, plasma medium-chain acylcarnitine levels and gene analysis of both ACADM alleles in subjects with suspected MCAD-deficiency." (PMID 19649258, 2009). "The medium-chain acyl-CoA dehydrogenase deficiency (MCADD) is caused by variants in ACADM gene." (PMID 40225143, 2023). "As clinical and laboratory findings resembled human patients and a previously published CKCS with suspected MCAD deficiency, we hypothesized that the phenotype in the affected dog was due to a variant in the ACADM gene." (PMID 36292732, 2022). "In our study, 6 ACADM mutations were found in 4 infants with MCAD deficiency." (PMID 31620161, 2019). "More than 70 mutations in ACADM gene have been found in patients with MCAD deficiency." (PMID 31620161, 2019). "ACADM (NM_000016.4), located at 1p31, is the only candidate gene causing MCAD deficiency." (PMID 26798524, 2015). "Based on available clinical and biochemical data together with current knowledge in humans, we propose the ACADM frameshift variant as causative variant for the MCAD deficiency with likely contribution to the neurological phenotype in the index case." (PMID 36292732, 2022). "We report on two siblings with mild MCAD deficiency associated with a novel splice site mutation in the ACADM gene." (PMID 26223887, 2015). "Medium chain acyl-CoA dehydrogenase deficiency (MCADD) is an inherited metabolic disease, characterized by biallelic variants in the ACADM gene." (PMID 40199742, 2025). "Medium-chain acyl-CoA dehydrogenase deficiency (MCADD), a potentially lethal metabolic disorder, is often associated with single-nucleotide polymorphisms (SNPs) in the acyl-CoA dehydrogenase, medium-chain (ACADM) gene." (PMID 41767627, 2026). "A 985A>G transition in ACADM has been identified as a common mutation associated with MCAD deficiency in Western Europe, however this mutation has not been identified in the Asian population." (PMID 29317722, 2018). "Since the introduction of neonatal screening for MCAD deficiency, a subgroup of newborns have been identified with variant ACADM genotypes that had never been identified before in clinically ascertained patients." (PMID 23509891, 2013).
MCAD deficiency (continued). "Since the introduction of NBS for MCAD deficiency, a new subgroup of newborns has been identified with variant ACADM genotypes that have not been seen before in clinically ascertained patients with classical ACADM genotypes." (PMID 23509891, 2013). "Currently, a late evening meal is advised during the first two years of life for patients with MCAD deficiency, regardless of the ACADM genotype." (PMID 23509891, 2013). "Our results, however, indicate that certain ACADM mutations do not categorically cause symptomatic MCAD deficiency." (PMID 23028790, 2012).
hepatocellular carcinoma (10 papers, 2021 to 2025). A malignant tumor that arises from hepatocytes. "ACADM, an acyl-CoA dehydrogenase, catalyzes mitochondrial fatty acid beta-oxidation and is differentially expressed in hepatocellular carcinoma, cholangiocarcinoma, and coronary microvascular dysfunction." (PMID 41187148, 2025). "Previous researches have demonstrated the importance of ACADM in the development of glioma and hepatocellular carcinoma, but its role in KIRC remains obscure." (PMID 38361759, 2024). "ACADM has been documented to possess tumor-inhibiting capabilities in hepatocellular carcinoma (HCC)." (PMID 39002673, 2024). "ACADM, an enzyme that catalyzes the first step of mitochondrial fatty acid-oxidation pathway, has been shown to inhibit the progression of hepatocellular carcinoma via regulation of CAV1 and SREBP121." (PMID 37460577, 2023). "Inhibition of ACADM can promote dysregulation of fatty acid oxidation, leading to hepatocellular carcinoma progression." (PMID 36059510, 2022). "Interestingly, we found that ACADM plays an anticancer role in most tumors such as hepatocellular carcinoma and neuroblastoma." (PMID 35873479, 2022). "Inhibition of ACADM could alter hepatocellular carcinoma cell lipid metabolism and promote cell lipid accumulation, ultimately drive hepatocarcinogenesis." (PMID 35141213, 2021). "Hepatocellular carcinoma (HCC) cells have been found to significantly under-express medium-chain acyl-coenzyme a dehydrogenase (ACADM), an enzyme that catalyzes the first step of mitochondrial fatty acid oxidation." (PMID 39126035, 2024). "Furthermore, according to the CPTAC dataset, the ACADM protein was downregulated in colon cancer, breast cancer, HNSC, clear cell RCC, pancreatic adenocarcinoma, and hepatocellular carcinoma but upregulated in lung carcinoma and UCEC (P < 0.001)." (PMID 38664460, 2024).
phenylketonuria (8 papers, 2017 to 2025). Phenylketonuria (PKU) is the most common inborn error of amino acid metabolism and is characterized by mild to severe mental disability in untreated patients. "However, we found a number of VUS in such known genes, including ACADM, ACADVL and CFTR, and this has also been shown previously for other disease genes included in NBS panels, including PAH gene for phenylketonuria and GALT for galactosemia." (PMID 34449524, 2021).
Obesity (6 papers, 2012 to 2026). Accumulation of substantial excess body fat. "Studies have shown that LXR receptor agonist T0901317 can up-regulate the expression of ACADM and other enzymes, thereby inhibiting the progression of obesity in mice." (PMID 38361759, 2024). "Therefore, REGγ regulates browning of WAT by degrading ACADM through ubiquitin‐ and ATP‐independent protein degradation pathways to induce obesity." (PMID 40971725, 2025). "Following, we showed increased protein levels of β-oxidation enzymes in malignant CAAT: elevated ACOX1 protein level characterized CAAT of women with malignant tumors, independently from obesity, while elevated ACADM protein level characterized only CAAT of obese women with malignant tumors." (PMID 38247846, 2024). "Overall, we revealed that REGγ regulates browning of WAT via ACADM and KLF15‐UCP1 signaling to modulate obesity." (PMID 40971725, 2025). "Overall, these results demonstrate that REGγ regulates the browning of white adipose tissue via ACADM and KLF15‐UCP1 signaling pathways to modulate obesity, providing new insights for the treatment of obese patients." (PMID 40971725, 2025).
breast carcinoma (5 papers, 2017 to 2024). "It had been reported that ACADM is associated with the progression of some tumors, especially those closely related to lipid metabolism, such as neuroblastoma and breast cancer." (PMID 35873479, 2022). "Silencing of ACADM expression has been shown to suppress the migration and invasion of breast cancer cells significantly." (PMID 37538114, 2023). "ACADM enhances the invasion and metastasis ability of breast cancer cells." (PMID 37538114, 2023). "However, it has been reported that ACADM enhances the invasion and metastasis ability of breast cancer cells." (PMID 35873479, 2022).
Hypoglycemia (4 papers, 2010 to 2013). A decreased concentration of glucose in the blood. "These events may retard the occurrence of fasting and hypoglycemia and explain the wide range of blood acylcarnitines (C8 and C8/C10 levels) in affected patients even if such levels are compared in different patients (Pt12 and Pt14) carrying the same (c.985A>G, p.Lys329Glu) ACADM gene mutation." (PMID 24294134, 2013).
liver cancer (4 papers, 2019 to 2024). An epithelial or non-epithelial malignant neoplasm that arises from the liver. "It has been suggested that ACADM can affect fatty acid oxidation in liver cancer, so ACADM was selected for further analysis." (PMID 38361759, 2024). "Yam’s research showed that when ACADM-mediated fatty acid β-oxidation is blocked, it can encourage the emergence of liver cancer." (PMID 37612627, 2023). "Similarly, downregulation of ACADM expression impedes fatty acid β oxidation, thereby facilitating hepatocellular invasion and promoting liver cancer progression." (PMID 38971783, 2024).
renal carcinoma (4 papers, 2019 to 2025). A carcinoma arising from the epithelium of the renal parenchyma or the renal pelvis. "In a study of prognostic features of renal cancer according to SARS-CoV-2 related genes, a model constructed with ACADM as one of the hub genes was linked with infiltration of multiple cells of immunity." (PMID 38361759, 2024). "In addition, ACADM has been shown as a potential biomarker for kidney cancer, and consistent with this study, ACADM is downregulated in renal cancer." (PMID 35873479, 2022). "In addition, immunohistochemistry staining in The Human Protein Atlas database showed that the expression of EHHADH, ACADM and AGXT2 proteins were also significantly lower in renal carcinoma compared to normal kidney." (PMID 31839812, 2019).
pancreatic cancer (3 papers, 2023 to 2025). "Recent studies suggest that the presence of medium-chain acyl-CoA dehydrogenase (ACADM) in exosomes derived from pancreatic cancer cells can be used as a marker for gemcitabine treatment sensitivity." (PMID 40328736, 2025). "Importantly, knocking down ACADM in pancreatic cancer cells could improve their sensitivity to gemcitabine treatment." (PMID 40328736, 2025).
colon cancer (2 papers, 2024). "ACADM is believed to be one of the important enzymes participated in amino acid metabolism of colon cancer tumor-associated macrophages (TAMs), and the elevated level of ACADM is linked with a more favorable outcome for colon cancer individuals." (PMID 38361759, 2024).
colorectal cancer (2 papers, 2020 to 2022). A primary or metastatic malignant neoplasm that affects the colon or rectum. "Therefore, we used the correlation of the expression level of genes with the prognosis of colorectal cancer patients as an evaluation index, and finally identified eight critical enzymes of amino acid metabolism in colon TAMs, namely, ACADM, ACADS, GPX4, GSR, HADH, HMGCL, HMGCS1 and IDH1." (PMID 36552870, 2022). "The genes in the reported colorectal cancer group include POLR1D, DGKB, SULT2B1 SMPD1 GOT2, MTHFD1L and ACADM." (PMID 32285560, 2020). "Also, ACADM might be involved in the regulation of the overall survival of colorectal cancer." (PMID 32285560, 2020). "Interestingly, the decreased expression levels of ACADM, GSR and HADH were closely related to the deterioration of colorectal cancer patients (p < 0.01)." (PMID 36552870, 2022).
diabetes (2 papers, 2011 to 2024). "Further investigation is needed before conclusive remarks can be appointed to the variants in ACADS and ACADM and their putative involvement in the pathogenesis of diabetes." (PMID 21211036, 2011). "The impact of ACADS rs2014355 and ACADM rs11161510 on OGTT-derived diabetes-related quantitative traits was evaluated in a random sample of glucose-tolerant individuals from the Inter99 cohort." (PMID 21211036, 2011). "Additionally, miR-16-2-3p appears to alleviate coronary microvascular dysfunction in diabetes by modulating ACADM-mediated fatty acid degradation in endothelial cells." (PMID 38336726, 2024). "In contrast, rs11161510 of ACADM did not associate with any of the examined quantitative traits or with diabetes in case-control analysis." (PMID 21211036, 2011).
fatty acid metabolic disorders (2 papers, 2021 to 2024). "Cyl-CoA Dehydrogenase Medium Chain (ACADM) catalyzes the β-oxidation of medium-chain fatty acids, and the deficiency of this gene can cause fatty acid metabolism disorders and liver function abnormalities." (PMID 38473080, 2024). "ACADM (medium-chain acyl-CoA dehydrogenase) participates in the initial steps of the mitochondrial fatty acid beta-oxidation pathway and is involved in pathways associated with fatty acid metabolic disorders." (PMID 33856140, 2021).
neuroblastoma (2 papers, 2022 to 2024). Neuroblastoma (NB) is the most common solid, extracranial childhood tumor. "Similarly, neuroblastoma patients with high ACADM expressions exhibit better overall survival (OS); the upregulation of ACADM and FAO by the tozasertib can suppress neuroblastoma progression." (PMID 38664460, 2024).
ACAD deficiency (1 paper, 2019). "In addition, 22 mutations, including 5 novel mutations and 17 reported mutations, in ACADS, ACADM, and ACADL genes were detected in 20 infants with ACAD deficiency by using high-thorough sequencing based on target capture." (PMID 31620161, 2019).
aortic valve disease (1 paper, 2016). "The expression of ACADM protein (1.81 ± 0.11 vs. 1.43 ± 0.09, P = 0.011) in the left atria was significantly up-regulated in the patients with aortic valve disease and heart failure (n = 6) compared to normal controls (n = 4)." (PMID 27250500, 2016). "The expressions of ACADM, FABP3, ECH1, ACAA2, EHHADH and CPT1A in the left atria were significantly up-regulated in the MR patients with heart failure compared to patients with aortic valve disease and heart failure and normal controls." (PMID 27250500, 2016). "Notably, only ACADM, FABP3, ECH1, ACAA2, EHHADH, CPT1A and PLTP of the PPAR signaling pathway were differentially expressed in the left atria of MR patients compared to patients with aortic valve disease and normal controls." (PMID 27250500, 2016). "Notably, seven genes (ACADM, FABP3, ECH1, ACAA2, EHHADH, CPT1A and PLTP) of the PPAR signaling pathway were differentially expressed in the left atria of MR patients compared to patients with aortic valve disease and normal controls." (PMID 27250500, 2016). "Notably, only ACADM, FABP3, ECH1, ACAA2, EHHADH, CPT1A and PLTP of the PPAR pathway were significantly differentially expressed in the MR patients compared to patients with aortic valve disease and normal controls." (PMID 27250500, 2016).
atherosclerosis (1 paper, 2025). A disease characterized by the build-up of fatty material and calcium deposition in the arterial wall resulting in partial or complete occlusion of the arterial lumen. "Immunohistochemical staining of mouse aorta and human datasets from public databases also showed that ACADM expression was significantly reduced in atherosclerosis." (PMID 41329250, 2025).